EPO (erythropoietin)
Diseases named in the same sentence as EPO in open-access papers (continued):
Sharing a sentence is not in itself a finding about the gene and the disease.
iron deficiency (continued). "In vitro, pan-histone deacetylase inhibition elevates hepcidin expression, and in vivo maintains H3K9ac at hepcidin-associated chromatin and abrogates hepcidin suppression by erythropoietin, iron deficiency, thalassemia, and hemochromatosis." (PMID 28864822, 2017). "Several mechanisms whereby malignancy induces low hemoglobin have been suggested, including blood loss, functional iron deficiency, and inflammation leading to reductions in renal erythropoietin production." (PMID 28881716, 2017). "The causes of renal anemia include decreased erythropoietin production, increased inflammation, mineral bone disorder, and shortened erythrocyte life span, as well as iron deficiency of either relative or absolute form." (PMID 27906969, 2016). "The aim of this study was to determine TMPRSS6 protein content in experimental animals subjected to iron deficiency, iron overload or erythropoietin (EPO) administration." (PMID 26845567, 2016). "We based our rationale on the findings of Brugnara, Chambers, Malynn, Goldberg & Kruskall, who showed healthy subjects with serum ferritin levels <100 μg·L-1 developed a functional iron deficiency when undergoing synthetic EPO administration." (PMID 26263553, 2015). "These include hemolysis of peripheral erythrocytes, iron deficiency through inefficient duodenal iron absorption leading to inhibition of heme synthesis, and renal anemia characterized by hypoproduction of erythropoietin." (PMID 26161863, 2015). "Physiologically, this response probably serves to contain EPO expression and subsequent stimulation of erythropoiesis under conditions of iron deficiency." (PMID 25120486, 2014). "This fraction is expected to increase in normoxic iron deficiency due to 4Fe-4S cluster disassembly, further suppressing HIF2α and EPO expression as a homeostatic response to reduced iron availability, consistently with iron-restricted erythropoiesis." (PMID 25120486, 2014). "As CKD progresses, Hgb falls because of a decrease in erythropoietin production as well as iron deficiency that develops secondary to decreased absorption and increased loss." (PMID 23514036, 2013). "Monitoring erythropoietin treated patients' iron status is important to detect iron deficiency and avoid the adverse effects of iron medication." (PMID 23555091, 2013). "Possible explanations for this seemingly paradoxical finding in the face of elevated EPO blood levels include tumour-induced EPO inactivity (or reduced activity), EPO hyporesponsiveness, iron deficiency and inflammation." (PMID 23305401, 2013). "Factors involved in EPO resistance that can be modulated include iron deficiency, hyperparathyroidism, inadequate dialysis and malnutrition." (PMID 22768256, 2012). "In this process, iron acts as a critical cofactor, with iron deficiency blunting EPO-responsiveness of erythroid progenitors." (PMID 21887333, 2011). "This “functional iron deficiency,” a term used to describe states of iron restricted erythropoiesis induced by exogenous erythropoietin, applies also to states of ineffective erythropoiesis with elevated endogenous erythropoietin." (PMID 20631898, 2010). "During the whole observation, mean Hb level was lower and EPO dose higher in patients with "absolute iron deficiency" compared to the group with "adequate iron status"." (PMID 19077225, 2008). "The group "functional iron deficiency" had the lowest Hb level at month 6 and 12, despite the use of the highest EPO dose (>200 IU/kg/week)." (PMID 19077225, 2008). "In the second subgroup of this study there was again a correlation between iron deficiency and erythropoietin levels; however, thrombocytosis in these patients was absent." (PMID 18380894, 2008). "Specifically, the increase in erythropoietin levels, triggered by iron deficiency, may drive the differentiation of stem cells into erythroid progenitor cells, ultimately reducing the pool of viable stem cells available for collection." (PMID 39997353, 2025).
iron deficiency (continued). "Iron deficiency is another common cause, partly attributed to the structural homology between erythropoietin and TPO, which may promote megakaryocyte proliferation in anemic states." (PMID 41552126, 2025). "Conversely, functional iron deficiency represents an inability to utilise adequate body iron stores, and is associated with inflammatory disease, renal disease, hepatic disease, and exogenous erythropoietin administration." (PMID 41463898, 2025). "Additionally, several other factors reduce the marrow's sensitivity to EPO, including inflammation and iron deficiency, which are the two most prevalent causes." (PMID 39958087, 2025). "In the preoperative setting, the early identification of iron deficiency and treatment with iron supplements or erythropoietin (EPO) have been shown to improve preoperative hemoglobin levels and decrease perioperative transfusion requirements in some pediatric surgical populations." (PMID 40003262, 2025). "High inflammation, malnutrition, and iron deficiency can lead to decreased production of erythropoietin (EPO) in the kidneys and reduced responsiveness of the bone marrow to EPO, potentially causing issues in bone marrow hematopoiesis and affecting bone quality." (PMID 40647430, 2025). "In addition to the well-known factors involved in the pathogenesis of renal anemia, such as decreased erythropoietin production and iron deficiency, eryptosis is also known to contribute to the development of this clinical condition." (PMID 40643488, 2025). "The supraphysiologic stimulation of erythropoiesis through injectable EPO may present with paradoxical findings, including low hemoglobin concentrations, apparent iron deficiency, or impaired mobilization of stored iron." (PMID 41012526, 2025). "In such cases, anemia is mainly caused by endogenous erythropoietin (EPO) and iron deficiencies." (PMID 39200348, 2024). "Iron deficiency, along with a shortage in erythropoietin, is a common cause." (PMID 39664943, 2024). "In addition to insufficient EPO production, iron deficiency plays a critical role in CKD-associated anemia." (PMID 37376162, 2023). "Moreover, CKD patients also have impaired dietary iron absorption, making oral iron supplements less effective than IV iron supplementation regarding improving iron deficiency and reducing EPO dose in HD patients." (PMID 37376162, 2023). "Therefore, monitoring and correction (if necessary) of iron deficiency by either oral or parenteral iron before starting EPO is recommended." (PMID 38029231, 2023). "Increasing evidence shows that the downregulation of hepcidin and upregulation of erythropoietin related to iron deficiency may have protective effects on the cardiovascular system and other organs." (PMID 36986113, 2023). "Splenomegaly, iron deficiency markers, and low erythropoietin supported PV investigation." (PMID 36779103, 2023). "The inflammatory molecules produce adverse effects on the cells of the hematological system, and these include iron deficiency, reduced EPO production and elevated phagocytosis of erythrocytes by hepatic and splenic macrophages, and also enhanced eryptosis by oxidative stress in the circulation." (PMID 37240288, 2023). "In CKD, iron deficiency may arise due to impaired absorption and diminished erythropoietin production, exacerbating RLS symptoms." (PMID 37893513, 2023). "This review article has discussed the multifactorial pathophysiology, including iron deficiency, longstanding inflammation, abnormal levels of human erythropoietin (Epo), and the abnormal activation of the renin-angiotensin-aldosterone system (RAAS) being the most significant." (PMID 36017290, 2022). "In addition to causing the hepcidin-mediated functional iron deficiency, posttransplant inflammation causes resistance to erythropoietin." (PMID 35795334, 2022).
iron deficiency (continued). "Furthermore, inflammation interferes with the body’s iron homeostasis through hepcidin and cause functional iron deficiency, which in turn increase EPO resistance." (PMID 35318873, 2022). "The etiology of iron deficiency in cardiac surgery patients involves insufficient iron uptake, an increase in hepcidin synthesis, inhibition of erythropoietin synthesis, and decreased sensitivity of erythroblasts to erythropoietin, which leads to poor preoperative hemoglobin level." (PMID 36483623, 2022). "An insufficient rise in erythropoietin to recompense aging marrow cells, loss of hematopoietic stem cells and iron deficiency due to dietary reasons particularly in our part of the world or because of frequent blood donations can be contributory factors in older blood donors." (PMID 35991248, 2022). "Previous reports suggest that iron may inhibit platelet maturation, whereas iron deficiency may affect platelet production through EPO or have a direct effect on megakaryopoiesis by resulting in megakaryocyte progenitor expansion." (PMID 35813388, 2022). "Several studies have shown that in almost all erythropoietin-treated patients, iron supplementation is needed because iron deficiency may contribute to erythropoietin hypo-responsiveness." (PMID 36060352, 2022). "However, elevated levels of hepcidin and reduced erythropoietin levels, the hallmark of inflammation‐induced iron deficiency anaemia, were reported in patients with T2D." (PMID 35844722, 2021). "The marked reduction in maternal and neonatal total-FGF23 concentrations after antenatal iron supplementation is in keeping with previous studies and is likely caused by a reversal of hypoxia and/or EPO-driven FGF23 gene expression in osteocytes that occurs in iron deficiency." (PMID 33675347, 2021). "Moreover, the reduced lifespan of red blood cells, iron deficiency, and erythropoietin-stimulating agents can lead to an undervaluation of glucose control." (PMID 34062938, 2021). "Another potential cause of higher EPO levels could be increased hemolysis and/or iron deficiency as a result of increased physical activity." (PMID 34827208, 2021). "As low hepcidin levels are likely to be due to diminished up-regulation of hepcidin in response to inflammation and iron deficiency (due to an increase of erythropoietin) in this population, hepcidin was suggested as a possible useful marker in guiding iron therapy." (PMID 32107492, 2020). "Under iron deficiency, the numbers of erythrocytes, reticulocytes, and the EPO level rise." (PMID 32451387, 2020). "Chronic overexpression of EPO can lead to iron deficiency, so to determine whether the iron deficiency was causing the elevated FGF23, mice were given iron dextran." (PMID 32982979, 2020). "Hepcidin may have potential to guide iron therapy in severely anaemic children because in this population there is diminished up regulation of hepcidin in inflammation and iron deficiency due to an increase in erythropoietin." (PMID 32107492, 2020). "In non-irradiated mice, we tested, with a negative outcome, whether CD71 expression in LSK cells would respond to administration of erythropoietin (EPO) or induction of a state of iron deficiency." (PMID 32258026, 2020). "There are many known reasons for resistance, of which iron deficiency is the main factor, followed by infection, malnutrition, secondary hyperparathyropathy, and EPO resistance can also be induced by autoimmune diseases, aluminum poisoning and angiotensin converting enzyme inhibitors." (PMID 32848738, 2020). "Studies have shown that many factors may be associated with EPO responsiveness such as serum albumin level, inflammatory response, secondary hyperparathyroidism, and iron deficiency." (PMID 33293895, 2020). "Notably, iron deficiency, high endogenous EPO, or administration of rhEPO still resulted in increased total FGF23 production and cleavage in CKD." (PMID 30971944, 2019).
iron deficiency (continued). "Many factors may explain this feature including iron deficiency, defect in the production of erythropoietin, decline in the response of bone marrow to erythropoietin, and a defect in the releasing of iron from reticulo endothelial system." (PMID 31057960, 2019). "Because functional iron deficiency often occurs in states of EPO-mediated erythropoiesis, we also analyzed whether the positive association between EPO and FGF23 might be, at least in part, mediated by TSAT and sTfR." (PMID 31170159, 2019). "Once iron deficiency and active bleeding are excluded, the diagnosis of EPO resistance is established, and a multiplicity of factors could be responsible for this." (PMID 31412807, 2019). "The results clearly indicate that in this experimental setting, the effects of iron deficiency and EPO administration on Hamp expression are additive–apparently, feeding of the iron deficient diet decreases liver iron content, whereas administration of EPO decreased plasma iron content." (PMID 30958854, 2019). "Because functional iron deficiency occurs in patients with significant EPO-mediated erythropoiesis or as a response to treatment with ESAs, we also aimed to assess the association between endogenous EPO levels, as a reflection of tissue hypoxia, and mortality." (PMID 31170159, 2019). "The most common causes are iron deficiency and insufficient erythropoietin (EPO) production." (PMID 30917125, 2019). "Therefore, we aimed to determine the associations between iron deficiency and higher EPO levels with mortality, and the potential mediating role of FGF23, in a cohort of community-dwelling subjects." (PMID 31170159, 2019). "Similar to iron deficiency, recent studies from our group and others have established that both endogenous and exogenous EPO may influence FGF23 production and metabolism in CKD patients." (PMID 31170159, 2019). "Our findings suggest that FGF23 could be involved in the association between functional iron deficiency and increased EPO levels and death." (PMID 31170159, 2019). "Interestingly, iron deficiency and erythropoietin administration had additive effect on hepcidin gene downregulation in the liver." (PMID 30958854, 2019). "Furin plays an important role in regulation of FGF23 cleavage in iron deficiency and inflammation, whereas under conditions of high EPO GalNT3 inhibition might augment cleavage." (PMID 30971944, 2019). "Our findings suggest that FGF23 could be involved in the pathophysiology of iron-deficiency–and EPO-mediated mortality in the population." (PMID 31170159, 2019). "Lastly, although erythropoietin is the key hormone driving erythropoiesis, the availability of iron influences bone marrow reaction, which itself is severely impaired by an absolute or functional iron deficiency." (PMID 29668766, 2018). "Iron deficiency may result from the expanding erythrocyte population with a lower-than-normal erythropoietin level, and may mask the diagnosis of PV." (PMID 30564468, 2018). "And by inhibiting hepcidin expression and reducing inflammation, ASP ameliorates functional iron deficiency and increases iron availability, which restores iron supply for hemoglobin synthesis and possibly improves the responsiveness and efficacy of EPO." (PMID 30108502, 2018). "Serum iron (22 μg/dL [normal range, 60–160 μg/dL]) and ferritin (5 ng/mL [normal range, 15–200 ng/mL]) were suggestive of iron deficiency, serum erythropoietin was 8 mU/mL (normal range, 4.0–18.5 mU/mL), and a Janus kinase 2 (JAK2) mutation analysis was positive for JAK2V617F." (PMID 30564468, 2018). "Limitations: As with all secondary observational analyses of clinical trial data, our study is limited by the inability to account for unknown and unmeasured confounding factors, including iron deficiency, and erythropoietin levels." (PMID 28713869, 2017).
iron deficiency (continued). "This may be related to intracellular iron deficiency as bone marrow erythroid precursors expressed higher levels of Tfr1 mRNA in this model, or it may represent a direct effect of higher levels of erythropoietin on Erfe expression." (PMID 28135344, 2017). "Low concentrations of iron and hemoglobin in maternal serum coexisting with high level of erythropoietin suggest that smoking could lead to subclinical iron deficiency and chronic hypoxia not only in mothers but also in fetus." (PMID 26785641, 2016). "However, the clear relationship between renal and extra-renal EPO production, iron deficiency, hypoxia and evolution of kidney lesions remain to be elucidated." (PMID 25867633, 2015). "Hence, HIF2α can sense hypoxia and iron deficiency, and then increases EPO expression and drives red blood production, a process that consumes large amounts of iron." (PMID 24982634, 2014). "Chronic cortisol exposure may suppress erythropoiesis, potentially by the down-regulation of erythropoietin mRNA expression in the kidneys, and may promote iron deficiency, thereby increasing the risk of anemia." (PMID 23472188, 2013). "The current results also build on previous findings in rodents relating psychological stress to plasma iron deficiency and diminished erythropoiesis, and on a clinical study which showed that the erythropoietin analogue Darbepoetin-α had a beneficial effect on depressive symptoms in HF patients." (PMID 23472188, 2013). "Other authors suggest that erythropoietin can be restricted by iron deficiency and patients discharged from the PCCU may have depleted iron stores and/or suffer from functional iron deficiency." (PMID 23509619, 2013). "Iron deficiency is the main cause of suboptimal response to erythropoietin in dialysis patients." (PMID 23555091, 2013). "A potential confounder of this study, if any, would be an exogenous administration of EPO analogues, which could suppress endogenous secretion of EPO and may mask any platelet changes with correction of iron deficiency." (PMID 23476772, 2013). "Functional iron deficiency (FID) may cause erythropoietin resistance in patients under hemodialysis (HD)." (PMID 24350091, 2013). "As expected, both iron deficiency and EPO administration caused a dramatic drop in Hamp mRNA." (PMID 22629388, 2012). "Furthermore, it has been shown that the concomitant administration of IV iron with EPO (which can cause iron deficiency) in hemodialysis patients significantly reduces the platelet counts, compared to patient receiving EPO alone." (PMID 22536520, 2012). "The physiology underlying this finding is controversial, as rh-EPO administration often leads to iron deficiency, leading to difficulty in determining whether elevated or exogenous EPO is a cause of thrombocytosis or simply a surrogate for iron deficiency." (PMID 22084665, 2011). "However, mean Hb of the group "absolute iron deficiency" increased from baseline to month 6 and 12, in parallel to a decrease of EPO requirements, suggesting that physicians attempted to correct for iron deficit." (PMID 19077225, 2008). "In contrast, we did not observe any Hb improvement over time in patients with" functional iron deficiency", despite increased use of EPO: this group had overall the lowest Hb (except at baseline, month 3, 4 and 8) together with the highest dose of EPO (except at baseline)." (PMID 19077225, 2008). "Thus, there has to be some kind of additional factor present in some iron-deficiency patients contributing to the stimulatory potential of erythropoietin on thrombopoesis." (PMID 18380894, 2008). "In addition, it is known that sTfR levels may not only be increased in iron deficiency with inadequate iron supply for erythropoiesis but also due to the use of erythropoiesis-stimulating agents such as EPO." (PMID 38696124, 2024).